IGHV6-1 (immunoglobulin heavy variable 6-1)
Description:
V region of the variable domain of immunoglobulin heavy chains that participates in the antigen recognition. Immunoglobulins, also known as antibodies, are membrane-bound or secreted glycoproteins produced by B lymphocytes. In the recognition phase of humoral immunity, the membrane-bound immunoglobulins serve as receptors which, upon binding of a specific antigen, trigger the clonal expansion and differentiation of B lymphocytes into immunoglobulins-secreting plasma cells. Secreted immunoglobulins mediate the effector phase of humoral immunity, which results in the elimination of bound antigens. The antigen binding site is formed by the variable domain of one heavy chain, together with that of its associated light chain. Thus, each immunoglobulin has two antigen binding sites with remarkable affinity for a particular antigen. The variable domains are assembled by a process called V-(D)-J rearrangement and can then be subjected to somatic hypermutations which, after exposure to antigen and selection, allow affinity maturation for a particular antigen.
Synonyms: IGHV61; VH
Gene: Immunoglobulin variable (V) gene on chromosome 14 (105,939,756 to 105,940,253, reverse strand). Ensembl gene ENSG00000211933.
Subcellular location: Secreted; Cell membrane
Gene Ontology:
Molecular function: antigen binding
Biological process: immunoglobulin mediated immune response
Cellular component: extracellular region; plasma membrane
Homologues: Paralogues in human: IGHV4-61 (63% identical), IGHV4-28 (62% identical), IGHV4-39 (61% identical), IGHV4-59 (61% identical), IGHV4-4 (60% identical), IGHV4-31 (60% identical), IGHV4OR15-8 (59% identical), IGHV4-34 (57% identical), IGHV2-5 (48% identical), IGHV2-70D (47% identical), IGHV3-72 (47% identical), IGHV2-70 (46% identical), and 65 more.
Diseases named in the same sentence as IGHV6-1 in open-access papers:
IGHV6-1 is named in the same sentence as 8 diseases in open-access papers, as found by Europe PMC text mining. Sharing a sentence is not in itself a finding about the gene and the disease.
IGHV6-1 shares sentences with these, for which no sentence is quoted: abdominal aortic aneurysm (1 paper); amoebiasis (1); dilated cardiomyopathy (1); hypertrophic cardiomyopathy (1); influenza (1); primary immunodeficiency (1); staphylococcus aureus infection (1); systemic lupus erythematosus (1).